MLANA (melan-A)
Diseases named in the same sentence as MLANA in open-access papers (continued):
Sharing a sentence is not in itself a finding about the gene and the disease.
tumor (continued). "Forty-eight percent and 95% of amelanotic tumours (n = 21) stained positive for Melan A and S100, respectively." (PMID 30314485, 2018). "In this study, immunohistochemical positivity to at least one of Melan A and S100 was required for all amelanotic tumours, even in the presence of convincing morphological features." (PMID 30314485, 2018). "Twenty-one tumours (42%) were completely amelanotic; all but one of them (95%) were positive to S100, whereas 10 cases (48%) expressed Melan A, including the S100-negative tumour." (PMID 30314485, 2018). "Melanoma-associated antigens include tumor-associated testis-specific antigens (e.g., MAGE, BAGE, and GAGE), melanocyte differentiation antigens (e.g., Melan-A/MART-1, tyrosinase), and aberrantly expressed or mutated molecules (e.g., CDK4, beta-catenin)." (PMID 29179523, 2017). "Several pathological and IHC features were examined including median tumour size, pigmentation, mitotic index, ulceration, necrosis, Melan A, S100, HMB-45 and C-KIT." (PMID 28443572, 2017). "In any case, the down-regulation of ERAD is of general importance, as it will affect not only the presentation of the Melan-A/MART-126-35 epitope but also the presentation of all other membrane protein-derived tumor epitopes generated by the ERAD pathway." (PMID 27143649, 2016). "The tumor cells were detected by immunostaining for tyrosinase + gp100 + Melan-A (together PanMel) or MCSP, and the T cells and cytolytic T cells by immunostaining for CD3 and CD8, respectively." (PMID 27484791, 2016). "Ma-Mel-63a cells expressed and efficiently presented the Melan-A/MART-126-35 tumor epitope, as revealed by TNF-α-release assays." (PMID 27143649, 2016). "In immunohistochemical study, epithelioid tumor cells expressed melanocytic markers: S-100 protein and Melan-A." (PMID 25890370, 2015). "Immunohistochemistry of both lesions shows the tumour cells to strongly express melan A, HMB45, smooth muscle actin (SMA), and caldesmon, with focal S100 expression." (PMID 25821471, 2015). "This type of tumor usually shows positive immunoreactivity for melanocytic markers, including S-100 protein, Melan-A and HMB-45." (PMID 24348822, 2014). "The liver perfusate contained Melan-A positive and RNA containing exosomes, with similar miRNA profiles among patients, but dissimilar miRNA compared to exosomes isolated from tumor cell cultures." (PMID 25510783, 2014). "While these cells are not identical to naturally-occurring anti-tumor T cells, the TCR used was derived from a cloned T cell derived from Tumor Infiltrating Lymphocytes with known anti-Melan-A/MART-1 specific cytotoxic activity." (PMID 25503774, 2014). "Nevertheless, effective T-cell mediated immune responses with clinical benefit can be mounted against tumor associated melanoma antigens including tyrosinase, MART-1/Melan-A, and mutated CDK4." (PMID 24883190, 2014). "In this assay, we evaluated the production of multiple cytokines (IFNα, TNFγ, and IL-2) and upregulation of LAMP-1 (CD107a) by tumor- (Melan-A/MART-1) specific T-cells." (PMID 24195078, 2013). "Immunostaining for HMB-45 and Melan-A were performed on two separate areas of the tumor and using two different chromogens, diaminobenzidine (DBA) and alkaline phosphatase (AP), and all showed negative staining of the tumor cells." (PMID 23628229, 2013). "Immunohistochemically, the tumor cells showed strong positivity for kertain, inhibin, vimentine, melan-A, neuron-specific enolase, chromogranin, and S-100 protein and focal positivity to epithelial membrane antigen." (PMID 22008415, 2011). "Enrichment of tumor antigens such as melan-A, Silv, carcinoembryonic antigen (CEA), and mesothelin is observed in tumor-derived exosomes when compared with whole cell lysates." (PMID 22190973, 2011).
tumor (continued). "Immunohistochemically, the tumor cells showed strong positivity for kertain, inhibin, vimentine, melan-A, neuron-specific enolase, chromogranin, and S-100 protein and focal positivity to epithelial membrane antigen (EMA)." (PMID 22008415, 2011). "The adrenal phenotype of this tumor was verified by the immunopositivity for a panel of immunohistochemical markers, namely, Melan-A, synaptophysin, calretinin, particularly on the well differentiated carcinomatous component." (PMID 20687934, 2010). "The molecular bases of the association of MGRN1, PMEL, MLANA, and TYRP1 expression within the tumor and patient survival remain speculative." (PMID 40004203, 2025). "Immunohistochemically, the tumor was positive for S-100, Melan A, HMB-45, and SOX-10." (PMID 41001300, 2025). "Consistent with our findings in tumour-bearing mice, EVPs derived from B16F10 and K7M2 caused a significantly higher level of vascular leakiness, as compared to EVPs from 4T1, Melan-A (normal melanocyte cell line), and primary osteoblasts which did not induce a significant response." (PMID 38853850, 2024). "In addition, EVs-VSV are enriched in immunity-related proteins and were demonstrated to partly restore the cytotoxic functions of human Melan-A-restricted CD8+ T cell clones compared with EVs from uninfected tumor cells." (PMID 39492948, 2024). "However, the literature also suggests that the diagnosis of a tumor of adrenocortical origin should be based on a combination of markers, which should include inhibin, melan-A, and calretinin." (PMID 39129823, 2024). "This tumor is usually positive for Pax8, melanocytic markers (melan-A and HBM-45), and cathepsin-K." (PMID 39502747, 2024). "Regarding pathogenesis, a cytotoxic action of CD8+ activated T-cells against healthy melanocytes that share specific antigens with tumor melanocytes, such as Melan-A or gp100, is speculated." (PMID 37370736, 2023). "Ten tumors had not only heterogeneous morphologies but also a broad immunohistochemical profile: the tumor cells consistently moderately to strongly expressed Melan-A, Vimentin and TFEB; however, they showed only weak–moderate positivity for HMB45, AE1/AE3, P504s and CD10." (PMID 36830782, 2023). "We identified UM-associated hybrid cells based on co-expression of melanocytic tumor proteins: Microphthalmia-associated transcription factor (MITF), Tyrosinase (TYR), Melan-A (MLANA), premelanosome protein (PMEL, GP100), 5-hydroxytryptamine receptor 2B (HTR2B) and the pan-leukocyte marker CD45." (PMID 38106024, 2023). "Furthermore, when combined with VLP vaccination against TAA, Melan-A, anti-tumor responses were robust with significant survival benefits." (PMID 35406595, 2022). "TEXs originate from tumour cells and may contain many tumour-specific antigens, such as melan-A, gp 100, carcinoembryonic antigen (CEA), and mesothelin." (PMID 33789758, 2021). "The initial diagnostic workup showed that the tumor was not immunoreactive for the melanoma marker MART-1 (melan-A; MLANA)." (PMID 33707600, 2021). "Tumor was positive for vimentin and melan-A and inhibin-α was moderate in occasional tumor cells." (PMID 34803919, 2021). "Tumor cells were positive for Melan A, Calretinin and Vimentin suggesting an adrenal origin." (PMID 34307221, 2021). "Histologically, the tumor showed the typical morphology and immune profile of an epithelioid malignant PEComa, i.e., co-expression of myogenic and melanocytic markers, such as desmin, Melan-A, and HMB45." (PMID 31309284, 2020). "Intralesional therapies, such as T-VEC, BCG, PV-10, and IL2 can promote neoantigen exposure (through viral antigens, HMB-PP, HMGB1 proteins, and melan-A, respectively), possibly turning weakly immunogenic tumors into strongly immunogenic tumors and promoting anti-tumor immunity." (PMID 32455916, 2020).
tumor (continued). "Furthermore, tumor EVs are similar to the tumor cells themselves, in that they can contain tumor specific antigens such as melan-A and carcinoembryonic antigen (CEA) that are capable of suppressing tumor-specific responses." (PMID 30895170, 2019). "Besides Melan-A peptide, all patients received additional peptides in their vaccine formulations, for targeting multiple tumor antigens." (PMID 31969886, 2019). "Amelanotic tumours were admitted upon immunohistochemical positivity for Melan A or S100." (PMID 30314485, 2018). "In a study by Steven Rosenberg’s group almost a decade ago, tumor-infilitrating T cells including MART-1/Melan-A-specific CD8+ T cells present in metastatic melanoma lesions were found to predominantly express PD-1, compared to T cells in normal tissues and peripheral blood." (PMID 29033936, 2017). "In immunohistochemical study, epithelioid tumor cells expressed S-100 protein and Melan-A." (PMID 25890370, 2015). "Jurkat cells transduced with a TCR specific for Melan-A/MART-1 showed increased IL-2 production when co-cultured with iHsp90-treated tumors than with untreated (control) tumor cells, as an indication of enhanced T cell recognition as a consequence of inhibited Hsp90 function." (PMID 25503774, 2014). "Immunohistochemically, the tumor cells were positive for S-100 protein, vimentin and Melan-A." (PMID 24348822, 2014). "In this study, authors observed expression of melanocytic markers, tyrosinase and melan A, in those cells, hypothesizing that lineage infidelity had occured during tumor progression." (PMID 23599796, 2013). "Next, we investigated whether the peculiarities observed for Melan-A-specific T-cells was a general feature of self/tumor-specific T-cells." (PMID 22347406, 2012). "The tumor cells were positive for S-100, Melan A, and HMB-45 antigen." (PMID 23024873, 2012). "The tumor cells were strongly positive for inhibin and Melan-A, supporting the adrenal origin." (PMID 23094172, 2012). "Vital tumour cells were strongly positive for Melan A in most cases." (PMID 14583759, 2003). "Tumour cells may also exhibit organoid arrangement, local associations with vessel walls (usually thick-walled vessels), and pigment and smooth muscle cell marker expression, including HMB45 and Melan-A." (PMID 38291475, 2024). "Thus, it was verified that the Melan A-positive cells were restricted to the tumor." (PMID 36766767, 2023). "Importantly, immunisation with Melan-A peptide through vaccination leads to a reduction on the population of cross-reactive T cells and an enrichment of antigen-restricted T cells that can react with the tumour." (PMID 37409132, 2023). "Some tumor sections were immunostained with ready-to-use primary antibodies against broad-spectrum cytokeratin (CK), vimentin, calretinin, Wilms tumor gene-1 (WT-1), D2–40, Paird box 8, synaptophysin, chromogranin-A, inhibin-α, S-100, Melan-A, HMB45, CD34, and Ki-67 (Maixin, Fuzhou, China)." (PMID 38115250, 2023). "However, as natural tumor-primed CD8 TILN clones showed much broader and variable reactivities toward the Melan-A/MART-126-35 peptide variants, resulting in heterogenous linear regression slopes, the R square correlative value as well as the average best-fit slope were weaker." (PMID 36032094, 2022). "However, on performing IHC, the tumor cells showed immunopositivity with Melan A and HMB45." (PMID 36654614, 2022). "Indeed, we could demonstrate for the first time the increase of Melan-A released in EVs after 48 h of treatment with MAPKi, which could mirror the described tumour cell surface increased expression." (PMID 36726591, 2022). "However, we were unable to identify either S-100 or Melan-A in multiple sections of the tumour." (PMID 28086809, 2017). "In addition, iHsp90 increased recognition of tumor cells by T cells specific for Melan-A/MART-1." (PMID 25503774, 2014).
tumor (continued). "Based on this background, we have explored the possibility of constructing innovative vaccine formulations for clinical tumour immunotherapy, by taking advantage of well-described HLA-A2.1-restricted peptides from the immunodominant Melan-A/MART-1 melanoma TAA and liposome technology." (PMID 14710238, 2004). "Immunohistochemistry supported the diagnosis, with tumor cells staining positively for S100, HMB45, Melan A, and P16, and negatively for Desmin, CD99, AE1/3, Cam5.2, CK7, Chromogranin, Calretinin, CD56, CD45, P63, and Synaptophysin." (PMID 40395262, 2025). "The positive expression of Melan-A, HMB-45 and SMA in tumor cells by IHC is reliable evidence for the diagnosis of HAML." (PMID 40641931, 2025). "Immunohistochemistry (IHC) analysis confirmed the expression of Melan-A, HMB-45 and SMA by the tumor cells." (PMID 40641931, 2025). "Immunohistochemistry confirmed the diagnosis, with tumor cells expressing S100, HMB45, and Melan A, markers essential for differentiating OMM from other oral neoplasms." (PMID 40395262, 2025). "CTCs can be identified by markers like melanoma-associated antigen 3 (MAGE-A3), melanoma cell adhesion molecule (MCAM), melan-A, and chondroitin sulfate proteoglycan (MCSP), which can provide insights into tumor progression and metastatic potential." (PMID 40002300, 2025). "Immunohistochemically, the tumor cells were positive for HMB-45, Melan-A, and smooth muscle actin, confirming the diagnosis of pancreatic PEComa." (PMID 41852007, 2025). "Immunohistochemically, the tumor cells were diffusely positive for PRAME and SOX10, focally positive for Melan-A, and very focally positive for HMB45." (PMID 40437181, 2025). "PEComa is a mesenchymal origin tumor with unique immunophenotypic features, and its typical pathological features are the expression of both melanocyte markers (HMB-45, Melan-A) and smooth muscle markers (SMA, Desmin)." (PMID 41551141, 2025). "Immunofluorescence staining of the cells shows that cells stably transmitted to 100 generations are positive for the specific IHC indexes MLANA, S100β, PNL2, TRP1, and TRP2, which is consistent with the results of the IHC indexes of canine tumor tissues." (PMID 38891124, 2024). "The mainly positive rates of immunohistochemical staining for various tumor markers were 97.2% (35/36) for HMB-45, 97.1% (34/35) for Melan-A, 88.5% (23/26) for SMA, and 86.7%(26/30) for CD34." (PMID 39220650, 2024). "To investigate then the effect of EVs from OV-infected tumor cells on immune cells, we used two human CD8+ T cell clones that are specific for a peptide derived from the tumor antigen Melan-A in the HLA-A∗0201 context." (PMID 39492948, 2024). "T cell responses against melanocyte-specific antigens such as melanosomal proteins involved in pigment synthesis (i.e., gp100, tyrosinase, MART-1/Melan-A, TRP1, and TRP2) correlate with tumor regressions and vitiligo in vivo in mice and patients with melanoma." (PMID 37891002, 2024). "Histologically, this tumor showed extremely pleomorphic polygonal to elongated spindle cells that co-expressed neuroendocrine markers and were positive for S100, HMB-45, and Melan-A." (PMID 39280438, 2024). "The tumor with melanin production was immunohistochemically positive for S-100, HMG-45, Melan-A, and SOX10." (PMID 38289480, 2024). "The immunohistochemistry analysis of the right plantar tumor showed diffuse positivity for SOX-10, HMB45, Melan-A, with weak S100 positivity in certain areas." (PMID 37352079, 2023). "Using tetramer staining in a cohort of Melan-A/MART-1 vaccinated melanoma patients allowed phenotypic and functional comparison of tumour reactive T cells in peripheral blood versus tumour." (PMID 37520560, 2023). "The main antigen taken into consideration was Melan-A (also known as MART1), classified among the top 20 tumor antigens fundamental for developing immunotherapy in different types of cancer." (PMID 37759505, 2023).
tumor (continued). "Hematoxylin and eosin staining showed atypical tumor cells accompanied by melanin deposition; immunohistochemically, the tumor cells were positive for melanocytic marker Human Melanoma Black 45 (HMB-45) and Melan-A." (PMID 37308154, 2023). "Tumor cells were positive for HMB45 and Melan A. According to the AJCC 8th edition, tumor wasT3aN0M0, G1, at least stage IIB." (PMID 35039080, 2022). "Tumour cells were also positive for CD10 (GM003, PathnSitu, RTU), and Melan A (A103, Thermofisher, RTU)." (PMID 34514562, 2022). "Tumor cell-macrophage hybrids express both macrophage (CD14, CD68, CD163, CD204, and CD206) and tumor-specific markers (ALCAM, MLANA, KRT, EpCAM, CXCR4, and CD44)." (PMID 35242760, 2022). "Immunohistochemical analysis of the original tumor sample and the PDCs confirmed the expression of melanoma markers (HMB-45, MART-1 (Melan A), and Tyrosinase) in the PDCs." (PMID 34837846, 2022). "In agreement, Stuge and co-workers observed a diversified Melan-A-specific CD8+ repertoire expanded after peptide-vaccination, although a significant proportion of these cells was unable to lyse tumor cells." (PMID 36550555, 2022). "The immunohistochemical study has shown undifferentiated tumor with positive antibody anti PS100 and anti-melan A evoking malignant sinonasal melanoma." (PMID 35371814, 2022). "On closer examination, MiTF, Melan-A, S100 and HMB45 staining revealed a cell line-specific distribution of tumor cells within the tissue models." (PMID 36175453, 2022). "The tumor showed positivity for SOX10, S100, and Melan-A and intensely expressed HMB45 in the pleomorphic component." (PMID 36289768, 2022). "As such, Melan-A and MELOE-1 antigen-specific T repertoires are among the most frequent for tumor antigen-specific T repertoires." (PMID 34120214, 2021). "This analysis revealed that tumor cells were positive for S-100 protein, HMB-45, Melan-A, and SOX10." (PMID 33478436, 2021). "Each patient received a combination of Melan-A and MELOE-1 polyclonal specific T-cells, whose specificity and anti-tumor reactivity were checked prior to injection, with subcutaneous IL-2." (PMID 34120214, 2021). "The diagnosis was confirmed immunohistochemically by strong positive reaction of the tumor cells to S100, SOX10, HMB-45, and Melan A. To confirm the presence of Bartonella organisms, PCR analysis was performed in 6 cases and was positive." (PMID 34165046, 2021). "In contrast, immunohistochemistry showed that the tumor cells were weakly positive for HMB-45 and Melan A, strongly positive for MART-1, S-100 and vimentin, and that the Ki-67 index was 35%." (PMID 32635366, 2020). "These cells expressed both primary melanocytic tumor markers (MLANA, ALCAM) and tumor-promoting M2 macrophage markers (CD206, CD208)." (PMID 32182935, 2020). "Retained expression of tumor antigens targeted by the vaccine was assessed by gene-expression microarray analysis, and Melan-A, MAGE-3, and gp100 were all confirmed to be expressed by the recurrent tumor." (PMID 31703593, 2019). "Expression of three of the four antigens targeted by the vaccine (Melan-A, MAGE-3, gp100) was detected in the pre-treatment tumor specimen by gene-expression microarray analysis." (PMID 31703593, 2019). "Immunohistopathological study showed that the tumor cells were positively expressing the antibodies of HMB45, Melan-A, and S100." (PMID 30792691, 2019). "Immunohistochemistry was performed to detect the expression of melanocyte markers (Melan A, HMB 45), and the Ki67 proliferation index of the tumor cells was 20–30%." (PMID 30782194, 2019). "Immunohistochemistry was performed on all the 3 tumors, revealing that the tumor cells were positive for TFE3 and Melan-A." (PMID 29901594, 2018). "In the immunohistochemical staining, tumor cells were positive for human melanin black 45 (HMB-45) and Melan-A and partially positive for alpha-smooth muscle actin." (PMID 29921303, 2018).